BBX (BBX high mobility group box domain containing)
Description:
Transcription factor that is necessary for cell cycle progression from G1 to S phase.
Synonyms: HBP2; MDS001; HSPC339; ARTC1
Tractability: PROTAC: UniProt records ubiquitination sites on it; ubiquitination databases record sites on it; its protein half-life has been measured.
Gene: Protein-coding gene on chromosome 3 (107,522,936 to 107,811,339, forward strand). Ensembl gene ENSG00000114439.
Subcellular location: Nucleus
Subcellular location (Human Protein Atlas): Nucleoplasm; Cytosol
Gene Ontology:
Molecular function: sequence-specific double-stranded DNA binding; DNA-binding transcription factor activity, RNA polymerase II-specific; RNA polymerase II transcription regulatory region sequence-specific DNA binding
Biological process: regulation of transcription by RNA polymerase II
Cellular component: nucleoplasm; chromatin; nucleus
Genetic constraint (gnomAD): Loss-of-function variants: 25 observed, 97.29 expected, observed/expected ratio (o/e) 0.26, 90% interval 0.19 to 0.36. The upper end of that interval is the gene's LOEUF score, 0.36, which puts it in group 1 of 6, group 1 being the genes least tolerant of losing a copy. Missense variants: 1,000 observed, 1,168.4 expected, observed/expected ratio (o/e) 0.86, 90% interval 0.81 to 0.9. Synonymous variants: 373 observed, 405.07 expected, observed/expected ratio (o/e) 0.92, 90% interval 0.85 to 1.
Homologues: Orthologues: chimpanzee BBX (99% identical), macaque BBX (99% identical), dog BBX (94% identical), rabbit BBX (94% identical), guinea pig BBX (92% identical), pig BBX (92% identical), rat Bbx (86% identical), mouse Bbx (85% identical), tropical clawed frog bbx (58% identical), zebrafish bbx (47% identical), Drosophila melanogaster bbx (19% identical). Paralogues in human: CIC (17% identical).
Diseases named in the same sentence as BBX in open-access papers:
BBX is named in the same sentence as 5 diseases in open-access papers, as found by Europe PMC text mining. Sharing a sentence is not in itself a finding about the gene and the disease. The quoted sentences say what the papers report.
bipolar disorder (1 paper, 2018). A disorder of the brain that causes unusual shifts in mood, energy, activity levels and the ability to carry out day-to-day tasks. "PrediXcan has been applied to bipolar disorder, resulting in the identification of two genes, PTPRE and BBX, for which predicted increased expression in whole blood and the anterior cingulate cortex, respectively, was associated with increased risk of bipolar disorder." (PMID 28847336, 2018).
hypophosphatemia (1 paper, 2024). Lower than normal levels of phosphates in the circulating blood. "Having established that Bbx deficiency causes hypophosphatemia, we examined putative BBX-mediated regulatory mechanisms for phosphate homeostasis." (PMID 39482539, 2024).
male infertility (1 paper, 2021). The inability of the male to effect fertilization of an ovum after a specified period of unprotected intercourse. "However, loss of BBX leads to apoptosis of postmeiotic spermatids, spermiogenesis defects and ultimately, male infertility." (PMID 34869354, 2021).
BBX also shares sentences with these, for which no sentence is quoted: Obesity (2 papers); Parkinson disease (1).